COPG2IT1 (COPG2 imprinted transcript 1)
Synonyms: CIT1; NCRNA00170; COPG2AS
Gene: Long non-coding RNA gene on chromosome 7 (130,538,954 to 130,546,900, forward strand). Ensembl gene ENSG00000286214.
Diseases named in the same sentence as COPG2IT1 in open-access papers:
COPG2IT1 is named in the same sentence as 5 diseases in open-access papers, as found by Europe PMC text mining. Sharing a sentence is not in itself a finding about the gene and the disease. The quoted sentences say what the papers report.
lung carcinoma (1 paper, 2020). "The results of immunohistochemical analysis showed that compared with the stage I lung cancer group, the expression levels of COPG2IT1 and HLA.DQA1 in the stage III lung cancer group were significantly increased, and the expression levels of LYN, C3 and TNFRSF17 were significantly decreased." (PMID 33215029, 2020).
non-small cell lung carcinoma (1 paper, 2020). A group of at least three distinct histological types of lung cancer, including non-small cell squamous cell carcinoma, adenocarcinoma, and large cell carcinoma. "LYN, C3, COPG2IT1, LA.DQA1, and NFRSF17 may be new immune markers to judge the prognosis of patients with non-small cell lung cancer." (PMID 33215029, 2020).
COPG2IT1 also shares sentences with these, for which no sentence is quoted: citrin deficiency (1 paper); infection (1); Parkinson disease (1).